INIP (INTS3 and NABP interacting protein)
Description:
Component of the SOSS complex, a multiprotein complex that functions downstream of the MRN complex to promote DNA repair and G2/M checkpoint. The SOSS complex associates with single-stranded DNA at DNA lesions and influences diverse endpoints in the cellular DNA damage response including cell-cycle checkpoint activation, recombinational repair and maintenance of genomic stability. Required for efficient homologous recombination-dependent repair of double-strand breaks (DSBs) and ATM-dependent signaling pathways.
Synonyms: SOSS-C; hSSBIP1; C9orf80; SSBIP1; HSPC043; MISE; SOSSC
Tractability: PROTAC: ubiquitination databases record sites on it; its protein half-life has been measured.
Gene: Protein-coding gene on chromosome 9 (112,683,926 to 112,718,149, reverse strand). Ensembl gene ENSG00000148153.
Subcellular location: Nucleus
Subcellular location (Human Protein Atlas): Nucleoplasm
Gene Ontology:
Molecular function: protein binding
Biological process: DNA damage response; DNA repair; double-strand break repair via homologous recombination; mitotic G2/M transition checkpoint; response to ionizing radiation
Cellular component: nucleoplasm; nucleus; site of double-strand break; SOSS complex
Genetic constraint (gnomAD): Loss-of-function variants: 1 observed, 4.12 expected, observed/expected ratio (o/e) 0.24, 90% interval 0.085 to 1.14. That is too few expected variants to judge how well the gene tolerates losing a copy. Missense variants: 30 observed, 38.8 expected, observed/expected ratio (o/e) 0.77, 90% interval 0.58 to 1.05. Synonymous variants: 16 observed, 14.9 expected, observed/expected ratio (o/e) 1.07, 90% interval 0.73 to 1.62.
Homologues: Orthologues: chimpanzee INIP (100% identical), macaque INIP (100% identical), dog INIP (99% identical), guinea pig INIP (99% identical), mouse Inip (96% identical), rabbit INIP (96% identical), rat Inip (89% identical), zebrafish inip (84% identical), pig INIP (70% identical), tropical clawed frog inip (63% identical), Drosophila melanogaster CG42374 (34% identical).
Diseases named in the same sentence as INIP in open-access papers:
INIP is named in the same sentence as 1 disease in open-access papers, as found by Europe PMC text mining. Sharing a sentence is not in itself a finding about the gene and the disease.
INIP shares sentences with these, for which no sentence is quoted: Fanconi anaemia (1 paper).